CD81 (CD81 molecule)
Diseases named in the same sentence as CD81 in open-access papers (continued):
Sharing a sentence is not in itself a finding about the gene and the disease.
Obesity (9 papers, 2018 to 2026). Accumulation of substantial excess body fat. "More importantly, CD81+ cells respond to the cold challenge by giving rise to new brite/beige positive adipocytes in the inguinal adipose tissue, while the loss of CD81 causes diet-induced obesity and other complications." (PMID 34935088, 2022). "In this same study, the authors discovered that whole-body deletion of CD81 in mice worsened the consequences of diet-induced obesity in white adipose tissue (eg, fibrosis, inflammation, and insulin resistance) by disrupting integrin signaling." (PMID 37753183, 2023). "For example, one study demonstrated that the loss of CD81, a marker of beige adipocyte progenitor cells, impairs the differentiation of beige adipocytes, but not brown adipocytes, leading to diet-induced obesity and insulin resistance." (PMID 38544573, 2024). "There was also a diminution of CD81 positive vesicles with obesity, especially in obese BAT." (PMID 36142750, 2022). "Another recent discovery has shown that CD81 supports the preservation of adipose tissue metabolic health during obesity, but it is not known to what extent CD81+ sEVs contribute to this phenomenon." (PMID 37753183, 2023). "The absence of CD81 leads to diet-induced obesity, insulin resistance, and adipose tissue inflammation." (PMID 37553709, 2023). "Moreover, no studies to date have described the impact of obesity on the abundance of circulating CD81+ sEVs or what effects circulating CD81 protein may have on recipient cells." (PMID 37753183, 2023).
ovarian carcinoma (9 papers, 2019 to 2025). A malignant neoplasm originating from the surface ovarian epithelium. "While CD81 (as well as CD9 and CD63) is not universally present in all EVs, our previous work has shown that preselecting a subpopulation of plasma EVs using CD81 can reproducibly detect ovarian cancer-associated biomarkers using these nano-engineered microfluidic chips." (PMID 37884576, 2023). "In ovarian cancer (OC), several studies have identified CD81 as an exosome marker, representing the release of exosomes from OC cells." (PMID 40604335, 2025). "Here, we employed CD81‐pHluorin to investigate mechanisms of EV release in ovarian cancer (OC) cells and report a novel role for the Ca2+‐permeable transient receptor potential (TRP) channel TRPC3 in EV‐mediated communication." (PMID 38938673, 2023). "One ovarian cancer patient (Ov1) plasma was clearly positive for EpCAM+-CD81+ EVs, followed by a moderate signal in samples from Br1 and Br2 patients and lower signals were observed for the rest of the patients." (PMID 35135541, 2022). "They demonstrated a 3–5-fold increase in EV-associated expressions of EpCAM, CA-125, CD9, CD81, and CD63 in ovarian cancer patients compared to healthy controls." (PMID 31212643, 2019). "When stable knock‐down CD81 ameliorated the growth of ovarian cancer, it is worth paying attention to whether Tim4+ TAMs change." (PMID 40604335, 2025). "Silencing CD81 expression in OC cells directly inhibited their proliferation, invasion and migration, simultaneously suppressed mitophagy in Tim4+ TAMs in a murine model of ovarian cancer through inhibiting the production of PCS." (PMID 40604335, 2025). "Although the role of CD81 in the drug resistance of ovarian cancer remains unclear, studies have indicated a correlation between CD81 and drug resistance in patients with gastric cancer." (PMID 37754253, 2023). "Thus, Tim4+ TAMs could give us a better understanding of CD81 in tumour‐promoting role in ovarian cancer." (PMID 40604335, 2025). "Aberrant expression of ANXA5, CD81, and RAB5C affects the sensitivity of ovarian cancer cells to platinum- and paclitaxel-based chemotherapeutic agents." (PMID 37754253, 2023). "Exosomes derived from ovarian cancer cells actively carry biological molecules, including the histocompatibility complex (MHC I), heat shock protein (HSP), and CD81." (PMID 35625852, 2022). "This platform was able to efficiently capture EVs by anti-CD81 antibody and discriminate plasma EVs derived from ovarian cancer patients (n = 7) from the healthy controls (n = 5) by the mixture containing three biomarkers (CD63, CD81, and EpCAM)." (PMID 31212643, 2019). "Therefore, ANXA5, CD81, and RAB5C may serve as therapeutic targets in drug-resistant ovarian cancer." (PMID 37754253, 2023). "To determine whether ROS influence the TME through tumor exosomal miRNAs, we treated ovarian cancer A2780 cells with or without H2O2, and purified A2780-derived exosomes characterized by positive exosomal markers CD63 and CD81, and a negative exosomal marker calnexin." (PMID 35086548, 2022).
Sepsis (9 papers, 2021 to 2025). Sepsis is defined as life-threatening organ dysfunction caused by a dysregulated host response to infection. "cD81 contributed the most, suggesting that its potential role in sepsis diagnosis is the most significant." (PMID 40258762, 2025). "In sepsis, CD81 expression is significantly increased, and its role in exosomes suggests a close association with inflammatory responses and immune regulation." (PMID 41359645, 2025). "Biomarkers of sEVs (CD63, CD9, CD81, Alix, and Tsg101) isolated from healthy control subjects and patients with sepsis were detected using western blotting." (PMID 38910259, 2024). "The presence of the exosome markers CD81 (tumor susceptibility gene), TSG101and CD63 was confirmed in both the sham and sepsis samples by Western blotting analysis, indicating the isolated particles were exosomes." (PMID 37256132, 2023). "In summary, CD81, RPL22, GYPE, and HSPB1 were screened and they are significantly associated with the immunity in sepsis-induced ARDS." (PMID 34898369, 2022). "Here, an in vitro experiment was designed in order to verify the expression and function of CD81 in sepsis-induced ARDS." (PMID 34898369, 2022). "CD14+/CD81+ BAL EV numbers were significantly higher in those patients with sepsis-related ARDS who died during the 30 days following ICU admission." (PMID 35234046, 2022). "CD14+/CD81+ BAL EV numbers were significantly higher in those patients with sepsis-related ARDS who died during the 30 days following intensive care unit admission (P = 0.027)." (PMID 35234046, 2022). "This suggests that a high CD14+/CD81+ sEVs count found in patients’ body fluids could be a potential biomarker for the severity of disease and mortality in sepsis-related ARDS." (PMID 41010852, 2025). "Overall, four new plasma biomarker candidates were found in sepsis-induced ARDS, and we verified that CD81 may play critical roles in the biological and immunological processes of sepsis-induced ARDS." (PMID 34898369, 2022). "In conclusion, we report that CD14+/CD81+ BAL EV are enriched in patients with sepsis-related ARDS compared with controls, and that an elevated CD14+/CD81+ BAL EV count is associated with increased mortality in patients with ARDS, although the sample size is modest." (PMID 35234046, 2022). "These targets, including ADAM17, CD81, CASP1, and MGMT, lay the foundation for further research into the mechanisms of action of Calculus Bovis in sepsis treatment." (PMID 40258762, 2025). "It was also found that CD81 and RPL22 in the green module were specific to sepsis-induced ARDS, and both of them were less expressed compared with the control group." (PMID 34898369, 2022). "In patients with sepsis-related ARDS, those who died within 30 days of intensive care unit (ICU) admission had a greater number of CD14+/CD81+ BAL EV than survivors (medians 3.43 × 108/mL vs. 9.54 × 107/mL, P = 0.027), however there is overlap between groups." (PMID 35234046, 2022). "The relationship between CD14+/CD81+ BAL EV and mortality in patients with sepsis-related ARDS is in keeping with previous studies showing that the degree of monocyte influx in ARDS can correlate with the severity of respiratory failure." (PMID 35234046, 2022). "Through searching the sepsis-related publication of the key genes, CCR7, CXCR3, FYN, CEACAM1, CD81, AMPH, HLA-DMA, and G protein-coupled receptors (GPR18) were considered to be key genes." (PMID 34484417, 2021). "The authors showed that patients with sepsis-related ARDS had a significantly higher number of CD14+ and CD81+ (CD14+/CD81+) sEVs, resulting from monocytes, than patients with sepsis without ARDS." (PMID 41010852, 2025). "Hence, ADAM17, CASP1, CD81, and MGMT are likely to be potential core targets in Calculus Bovis treatment for sepsis." (PMID 40258762, 2025).
Sepsis (continued). "Ultimately, by taking the intersection of the results from the three machine learning methods, we identified six feature genes in sepsis: CD81, CLU, GLRX, CKAP4, DPEP2, and BCL11B; and seven feature genes in atrial fibrillation: LDHB, CD81, PFKFB2, CKAP4, CXCR4, DPEP2, and RORA." (PMID 41359645, 2025). "The analysis of immunofluorescence images and tissue-specific expression data revealed the different expression patterns of ADAM17, MGMT, CD81, and CASP1 at the cellular level and tissue level, which lays the foundation for further investigation of their roles in sepsis." (PMID 40258762, 2025). "Heatmaps revealed that the expression levels of CD63, CD9, CD81, Tsg101, EEA1, Rab5, and Rab7 in lung macrophages were significantly higher than those in neutrophils in the healthy control sEV group and sEVs from patients with sepsis." (PMID 38910259, 2024). "In this study, patients with sepsis-related ARDS had significantly higher numbers of CD14+/CD81+ BAL EV than patients with sepsis without ARDS." (PMID 35234046, 2022). "Thus, CD14+/CD81+ BAL EVs are a potential biomarker for disease severity and mortality in sepsis-related ARDS." (PMID 35234046, 2022). "Patients with sepsis-related ARDS had significantly higher numbers of CD14+/CD81+ monocyte-derived BAL EV than patients with sepsis without ARDS (P = 0.015)." (PMID 35234046, 2022). "Characterization studies showed that a greater number of monocyte-derived CD14+/CD81+ EV were present in the BAL of patients with sepsis-related ARDS compared to patients with sepsis without ARDS (medians 1.23 × 108/mL vs. 6.26 × 107/mL, P = 0.015)." (PMID 35234046, 2022).
B cell lymphoma (8 papers, 2013 to 2025). "CD81 signaling contributes to the development of solid tumors (notably colorectal, liver and gastric cancers) and has been implicated in the aggressivity of B-cell lymphomas." (PMID 37046846, 2023). "Our efforts to unveil the CD81 expression machinery have helped to shed new light on not only B cell development but also the improvement of molecular targeted therapy against B cell lymphoma using anti-CD81 antibodies." (PMID 34824296, 2021). "Tetraspanin CD81 was initially discovered by screening monoclonal antibodies elicited against a human B cell lymphoma for their direct anti-proliferative effects." (PMID 34824296, 2021). "If CD81 gene expression could be controlled by ON or OFF Pax5-expression, Pax5-mediated CD81 regulation may be useful for the treatment of B cell lymphoma using anti-CD81 antibodies." (PMID 34824296, 2021). "We observed altered gene expression in the hyperexpanded clone at relapse, including increase of CCR7, which might play a role in the emigration of malignant B cells from the brain to the CSF, and CD81, which has been identified as a novel immunotherapeutic target for B cell lymphomas." (PMID 36153593, 2022). "A study examining several B cell lymphoma cell lines found no CD9 expression and variable CD63 and CD81 levels." (PMID 33513976, 2021).
gastric cancer (8 papers, 2015 to 2023). A primary or metastatic malignant neoplasm involving the stomach. "The role of CD81 and other tetraspanins in antitumor immunity reinforces the interest for the targeting of these proteins to combat cancer, notably virus-associated cancers such as gastric cancer." (PMID 37046846, 2023). "CD63 and CD81, which are exosome marker proteins, were evaluated in cell lysates and exosome samples from gastric cancer cell lines." (PMID 33198173, 2020). "Western blotting analysis of CD63 and CD81 of exosomes from EBV-infected gastric cancer cell lines indicated an increase in exosome secretion." (PMID 33198173, 2020). "Therefore, CD81 has anti-proliferative and pro-apoptotic functions in gastric cancer cells and acts as a tumor suppressor gene." (PMID 34222025, 2021). "In general, the expression of TSPAN8, CD151, TSPAN1, and TSPAN4 is increased in gastric cancer tissues and enhance the proliferation and invasion of gastric cancer cells, while CD81, CD82, TSPAN5, TSPAN9, and TSPAN21 are downregulated and suppress gastric cancer cell growth." (PMID 34222025, 2021). "However, in gastric cancer, CD81 is assessed as a tumor suppressor gene and CD81 downregulation is related to the malignant progression of the tumors." (PMID 34222025, 2021). "We also discuss several tetraspanins, including CD81, CD82, TSPAN5, TSPAN9, and TSPAN21 that suppress gastric cancer cell growth." (PMID 34222025, 2021). "Taken together, CD81, CD82, TSPAN5, TSPAN9, and TSPAN21 are regarded as tumor suppressors in gastric cancer to inhibit tumor cell growth and invasion, and enhance the sensitivity to apoptotic stress signals." (PMID 34222025, 2021). "On the other hand, CAFs from scirrhous-type gastric cancer secretes exosomes CD81-negative/CD9-positive, which can promote cancer cell migration and invasion by activating the MMP2 signaling pathway." (PMID 33899109, 2021).
chronic hepatitis C (7 papers, 2012 to 2023). "For example, the EV CD81 fraction in serum was found to be highly increased in patients with chronic hepatitis C, which was found to be associated with inflammatory activity and severity of fibrosis." (PMID 32605316, 2020). "CD81 is increased in the exosomal serum fraction in patients with chronic hepatitis C and appears to be associated with inflammatory activity and severity of fibrosis." (PMID 22355327, 2012). "CD81 in the exosomal fraction in patients with chronic hepatitis C appears to be associated with inflammatory activity." (PMID 22355327, 2012). "This may indicate that increase of soluble CD81 in patients with chronic hepatitis C is mostly related with HCV associated necroinflammation." (PMID 22355327, 2012). "For instance, the expression of CD81 in serum exosomes of patients with chronic hepatitis C was significantly higher than that in the healthy volunteers and patients in the virus response phase." (PMID 34054552, 2021). "CD81 has also been shown to be elevated in exosomal serum fractions of patients with chronic hepatitis C, and the CD81 levels correlated with ALT levels and severity of liver fibrosis." (PMID 32605316, 2020). "Soluble CD81 was increased in patients with chronic hepatitis C compared to healthy subjects (p = 0.03) and cured patients (p = 0.017)." (PMID 22355327, 2012). "Another explanation for the increase of soluble CD81 levels in patients with chronic hepatitis C is secretion of CD81 containing exosomes by lymphocytes." (PMID 22355327, 2012). "In the present study, soluble CD81 levels were increased in the exosomal serum fraction p5 in patients with chronic hepatitis C compared to healthy volunteers." (PMID 22355327, 2012). "Increased soluble CD81 levels were significantly higher in patients with chronic hepatitis C." (PMID 33151933, 2020). "In the present study, patients with chronic hepatitis C and persistently normal ALT levels showed lower CD81-p5 levels than patients with chronic hepatitis C and elevated ALT levels and comparable levels of CD81-p5 with healthy controls and patients with cured HCV." (PMID 22355327, 2012). "Potential interaction of PBMC released CD81 exosomes with HCV particles may occur and influence hepatic inflammation in chronic hepatitis C. Here, further studies defining the source of soluble CD81 in HCV infection are necessary." (PMID 22355327, 2012). "Overall, the CD81-p5 level was associated with serum ALT activity in patients with chronic hepatitis C with or without ALT elevation (r = 0.372, p = 0.003)." (PMID 22355327, 2012). "In patients with chronic hepatitis C, CD81-p5 was neither associated with patients characteristics such as age and gender." (PMID 22355327, 2012).
neuroblastoma (7 papers, 2013 to 2022). Neuroblastoma (NB) is the most common solid, extracranial childhood tumor. "Neuroblastoma patients with GD2+/CD81+/CD56+/CD45– cells in BM by FMC had significantly worse event-free survival and increased cumulative incidence of relapse/progression." (PMID 31214500, 2019). "However, once combined with other molecules, CD81 contributed to the discrimination of neuroblastoma and PNET." (PMID 23472067, 2013). "While the role of CD81 displayed on CTCs is largely understudied, previous studies have used CD81+/CD56+/CD45− markers to detect neuroblastoma cells in the peripheral blood of patients." (PMID 36193887, 2022). "Tspan28 (CD81) knockout cells show impaired viral DNA replication and produce greatly diminished viral titers in Herpes simplex virus 1 infection in a neuroblastoma cell model." (PMID 35046772, 2021). "The first multiparameter FCM application for neuroblastoma cell detection was based on CD9+/CD56+/CD45– immunophenotype, which was later replaced by CD81+/CD56+/CD45– immunophenotype." (PMID 31214500, 2019). "By flow cytometry we confirmed the neuroblastoma phenotype of four TICs as they showed positive membrane expression of CD56, GD2, and CD81." (PMID 26452036, 2015). "Among our cases, CD81 and CD9 showed a variable and heterogeneous pattern of expression with limited utility as individual markers, in the differential diagnosis between neuroblastoma and other pediatric tumors." (PMID 23472067, 2013). "Other less specific markers such as CD56, CD9, CD57, CD81, CD99 also contributed to some differential diagnoses, e.g. the distinction between neuroblastoma and RMS (CD56,CD57,CD81) and between PNET and both RMS (CD9) and neuroblastoma (CD99, CD56, CD81 and CD57)." (PMID 23472067, 2013). "Similarly, several studies have evaluated the utility of CD81 and CD9 (together with CD45− and CD56+), for the discrimination between neuroblastoma cells and BM hematopoietic cells, for staging purposes, without extending such analysis to other subtypes of pediatric solid tumors." (PMID 23472067, 2013). "Using confocal imaging, we confirmed that LGALS3BP co-localizes with the exosome markers CD-63 and CD-81 and its mature form is enriched in exosomes/EVs isolated from SKNAS but not hNB neuroblastoma cells, providing an opportunity for specific targeting with 1959 antibody." (PMID 33076448, 2020).